MSH6 (mutS homolog 6)
Diseases named in the same sentence as MSH6 in open-access papers (continued):
Sharing a sentence is not in itself a finding about the gene and the disease.
colorectal cancer (continued). "The binding of MSH6 to the PD-L1 promoter was further validated in two additional human cancer cell lines, including SW620 (colorectal cancer) and SNU119 (ovarian cancer)." (PMID 40651337, 2025). "This test uses antibodies against four MMR proteins (MLH1, MS2, MSH6, and PMS2) to assess their expression in colorectal cancer tissue." (PMID 39741510, 2024). "On the other hand, evidence has shown colorectal cancer cells possessing disrupted MLH1 and MSH6 confer similar sensitivity to oxaliplatin as wild-type cells." (PMID 35685436, 2022). "It was found that the top 3 KEGG pathways with significant MSH6 enrichment were mismatch repair, CDDP drug resistance, and colorectal cancer." (PMID 35693981, 2022). "MSH6 coexpressed with two DElncRNAs (LOC105374879 and CASC15) and BCL2 coexpressed with B3GALT5‐AS1 were significantly enriched in the colorectal cancer signaling pathway." (PMID 31116002, 2019). "Mutations in the DNA mismatch repair genes, such as MLH1 (human mutL homolog 1) and MSH6 (human mutS homolog 6), have been reported in NF1 cases with malignant lymphoma, early-onset CNS tumors, and colorectal cancer." (PMID 22236362, 2012).
colorectal cancer (continued). "The SIR of colorectal cancer was also elevated in male MSH6 carriers, although not showing statistical significance." (PMID 32448342, 2020).
endometrial cancer (188 papers, 2005 to 2026). Primary or metastatic malignant neoplasm involving the endometrium (mucous membrane that lines the endometrial cavity). "One patient who developed breast cancer first and endometrial cancer later carried a novel frameshift variant in MSH6." (PMID 39400928, 2025). "Of the gene-disease associations not reported previously, associations reaching exome-wide associations using all methods included MSH6 for endometrial cancer, ATM for prostate cancer, and MED9 (MIM: 609878) for melanoma." (PMID 40073867, 2025). "In our current study, 55% of women (11 in 20) with pathogenic MSH6 variants had a prior diagnosis of endometrial cancer." (PMID 39518119, 2024). "Previous studies have indicated that, in comparison to other MMR mutations, the cumulative risk of endometrial cancer was highest among MSH6 carriers." (PMID 39518119, 2024). "The downregulation of PR (progesterone receptor), and MSH6 are consistent with the observation that high muscle/high adiposity is associated with worse outcomes among patients with endometrial cancer." (PMID 39766121, 2024). "For example, 18.2% (2 out of 11) of females with pathogenic MSH6 variants had endometrial cancer, while 36% of those with pathogenic MLH1 variants had a personal history of CRC, and 23% had a family history of CRC." (PMID 39518119, 2024). "In one study report, two cases of recurrent POLE ultra-mutated and MSH6 hyper-mutated endometrial carcinoma refractory to conventional surgical and chemotherapeutic treatments were effectively treated with the anti-PD-1 monoclonal antibody Nivolumab." (PMID 38893147, 2024). "For women with MSH6 GPVs, the risk of developing ovarian cancer only starts to increase in the post-menopausal years, in contrast to an earlier onset risk for endometrial cancer." (PMID 37258796, 2023). "The risk of developing Lynch syndrome-related tumors varies depending on the gene, and the risk of developing endometrial cancer is known to be relatively high in patients with MSH6 pathogenic variants." (PMID 37599324, 2023). "The second place takes the mutations in MLH1 (up to 40% in colorectal and 30% in endometrial cancer) and MSH6 (up to 5–10% in colorectal and 30% in endometrial cancer)." (PMID 37190216, 2023). "Studies have previously suggested MSH6 as a potential prognostic marker in endometrial cancer, where high MSH6 in hysterectomy tissue is associated with poor outcome and non-endometrioid subtype." (PMID 36482191, 2023).
endometrial cancer (continued). "Three of our BRCA1 mutation carriers also had breast cancer (and one additional cervical cancer), and one MSH6 mutation carrier also had endometrial cancer, in line with the known role of these genes in different types of DNA repair and cancer predisposition." (PMID 37013556, 2023). "Individuals with a mutation in MSH6 have an increased chance of endometrial cancer with an age of onset higher than 50 years." (PMID 36553592, 2022). "On the other hand, the major limitation of microsatellite instability testing is less accuracy in identifying endometrial cancer patients with the MSH6 mutation." (PMID 34048176, 2021). "LS-related endometrial cancer accounted for 4.78-5.4 % of total Chinese endometrial cancer, and MSH6 was likely to be a Chinese founder mutation for endometrial cancer." (PMID 33933134, 2021). "Of patients manifested MSH6 deficiency, 2 cases (2/9, 22.2%) developed endometrial cancer, one case (1/9, 11.1%) developed gastric cancer in LS group; 2 cases (1/6, 33.3%) developed gastric cancer." (PMID 32973888, 2020). "Women with MSH6 mutations with endometrial cancer were older compared to women carrying other mutations." (PMID 32854222, 2020). "On the other hand, path_MSH6 carriers showed high endometrial cancer risk and a modestly increased CRC risk, and path_PMS2 carriers showed a lower risk of any cancer." (PMID 32549215, 2020). "In path_MSH6 carriers the cumulative risk for endometrial cancer is high, while the risk for CRC is much lower both in men and women." (PMID 32190163, 2020). "One patient with optic glioma and a history of early-stage endometrial cancer had an MSH6 germline mutation." (PMID 32914008, 2019). "This is also the case for tumour-specific signature extractions of 52 colorectal and 44 endometrial cancers, both being cancer-types that are associated with MSH6 mutations." (PMID 29717121, 2018).
endometrial cancer (continued). "Carriers with MSH6 germline mutations appear to have a high risk of endometrial cancer but low risk of colorectal cancer." (PMID 30069056, 2018). "Surveillance can be tailored to individual women since MSH6 carriers have a high risk of endometrial cancer but a lower risk of OC." (PMID 28065618, 2017). "The MSH6 p.Leu585Pro mutation is associated with a nearly 50% lifetime risk of endometrial cancer and a 36% and 25% risk of CRC in males and females as well as a ∼12% lifetime risk of brain cancer (glioma)." (PMID 28466842, 2017). "This is a known pitfall in MSI testing for gynecologic cancers given a larger proportion of endometrial cancers harbor MSH6 mutations compared to CRC." (PMID 28259170, 2017). "In this study, three out of four patients (ID–050, ID-2-13, ID–032) with pathogenic MSH6 mutations had cancer early in life, and patient LS–050 had endometrial cancer as her first tumor at the age of 49, which is a hallmark of MSH6 mutation carriers." (PMID 26437257, 2015). "Germline mutation in the MSH6 gene is associated with the highest risk for developing endometrial carcinomas." (PMID 26161390, 2015). "We identified germline mutations in BRCA1 and in MSH6 in a patient with increased risk for HBOC diagnosed with endometrial cancer at the age of 46 years." (PMID 23164213, 2012). "The estimated cumulative risk of CRC at age 70 years was 61% (similar in males and females) and 65% for endometrial cancer in MSH6 mutation carriers." (PMID 20487569, 2010). "The median age of endometrial cancer in this study was 59 years, supporting the much later onset of cancer in MSH6 mutation carriers." (PMID 20487569, 2010). "Of the six families with a strong family history of endometrial carcinoma (two or more cases within the family), five (83%) were diagnosed with an MSH6 mutation." (PMID 20028567, 2009). "We also found a loss of expression of MSH6 in one MSI endometrial cancer sample." (PMID 40342963, 2025). "This could be partially explained by the fact that initially, MSH6 carriers were thought to have a higher endometrial carcinoma risk and were thus more actively counselled to have a prophylactic hysterectomy in The Netherlands." (PMID 39816931, 2025). "Furthermore, increasing evidence has shown that endometrial cancer is associated with MSH6 variants, possibly because the average life expectancy of women is higher than that of men." (PMID 38280988, 2024).